TNF (tumor necrosis factor)
Diseases named in the same sentence as TNF in open-access papers (continued):
Sharing a sentence is not in itself a finding about the gene and the disease.
migraine (continued). "In examining TNF-α, many studies during migraine attacks have reported unchanged levels compared to the interictal period, while others confirmed significant differences." (PMID 37176049, 2023). "They did find a trend for the pro-inflammatory cytokines TNF-α and IL-6 to be higher, and the anti-inflammatory cytokine IL-10 to be decreased, in the interictal period in migraine compared to healthy controls." (PMID 37016284, 2023). "To summarize, the relationship between changes in TNF-α and other cytokines and migraine pathogenesis is uncertain." (PMID 36982428, 2023). "Peripheral levels of pro-inflammatory cytokines, such as interleukin-1β (IL-1β), IL-6, IL-8, and tumor necrosis factor-α (TNFα) were elevated in patients with migraine." (PMID 37287623, 2023). "The proinflammatory cytokines IL-6, TNF-α, and IL-8 are higher in patients with migraine than healthy controls, and IL-1β levels are raised during migraine attacks." (PMID 37016284, 2023). "SD as the electrophysiologic event underlying migraine attacks has been demonstrated to further temporarily upregulate pro-inflammatory cytokines such as IL-6, IL-1β and TNF-α during migraine attacks." (PMID 37596546, 2023). "In agreement, data from the NTG animal model of migraine report higher protein levels or gene expression of proinflammatory cytokines (e.g., IL-1β, IL-6, and TNF-α) in the peripheral blood and trigeminovascular areas." (PMID 36982428, 2023). "Elevated levels of the pro-inflammatory cytokines IL-6, IL-8, and TNF-α are commonly observed in patients with migraine." (PMID 37098498, 2023). "During migraine attacks (ictal period), elevated TNF-α levels in CSF have been observed in patients with chronic migraine despite normal serum TNF-α levels." (PMID 37176049, 2023). "A clinical study of migraine patients revealed that the plasma levels of TNF-alpha, IL-1beta, and IL-10 were significantly higher ictally versus interictally." (PMID 36835524, 2023). "Given that the -308 G > A polymorphism is thought to affect the TNF-α gene's promoter activity and that the gene is part of the major histocompatibility complex, this variant could interfere with immunologic equilibrium and impact migraine genesis, development, or progression." (PMID 37085790, 2023). "An association of inflammatory cytokines and migraine was revealed by a recent meta-analysis, that concluded higher levels of pro-inflammatory cytokines IL-6, IL-8 and TNF-α were detected in migraine patients compared to control subjects." (PMID 37940864, 2023). "Studies conducted on animal models have provided a possible link between IR and migraine, considering that several vascular mediators, interleukins or cytokines (TNF-α, C-reactive protein, IL-1β, IL-6, and IL-8), have an important role in both IR and migraine." (PMID 37886939, 2023). "In support of this notion, a recent preclinical study demonstrated that microbiota dysbiosis enhanced migraine-like pain via upregulation of the proinflammatory cytokine tumor necrosis factor alpha (TNFα) in intraspinal trigeminal nucleus caudalis (Sp5C)." (PMID 37792173, 2023). "The two most commonly measured cytokines (IL-6 and TNF-α) were both higher in migraine than controls." (PMID 37016284, 2023). "During migraine attacks, increased levels of pro-inflammatory cytokines such as TNF-α and IL-1β have been detected in the serum." (PMID 37755364, 2023). "For example, supplementation with ω-3 fatty acids and nano-curcumin, reduced expression, and serum levels of TNF-α in addition to reducing migraine attack frequency." (PMID 36908624, 2023). "TNF-alpha is a pro-inflammatory cytokine that appears to play a role in migraine pathogenesis by simulating Calcitonin gene-related peptide (CGRP)." (PMID 37085790, 2023). "A recent in vivo study induced a rat migraine model with dural electric stimulation and found an increase in serum inflammatory factors, including IL-1β, TNF-α and IL-6." (PMID 37190506, 2023).
migraine (continued). "The role of cytokines in migraine is evidenced by the effectiveness of NSAIDs in symptomatic therapy, by the presence of ictal and interictal increased plasma levels of TNF-α and IL-6 and increased levels of TNF-α in CSF." (PMID 36614097, 2022). "These reactions can further increase the inflammatory cytokines (such as 5-HT, IL-6, and TNF-α) in cerebral microvascular endothelial cells, and finally lead to migraine." (PMID 36619923, 2022). "In our ex vivo preparation, pro-inflammatory cytokines (i.e., IL-6, IL-10, MCP-1, TNFα, IL-12p70, and IFNγ) are released and detectable already at basal conditions, confirming the local source of inflammatory stimuli that can trigger migraine." (PMID 35614095, 2022). "Tumor necrosis factor α (TNF-α) was elevated during attack in migraine patients with aura, and baseline levels were increased in general migraine patients." (PMID 35432179, 2022). "The body of migraine patients was in a state of microinflammation, and the serum levels of TNF‐α, IL‐6, and hs‐CRP were at a high level." (PMID 35791513, 2022). "The most relevant cytokines related to migraines include IL-1, IL-2, IL-4, IL-6, IL-10, TNF-α, and TGF-β." (PMID 35896985, 2022). "Several major cytokines, including IL-1β, IL-6 and tumor necrosis factor (TNF), have been thought to be linked to migraine pathophysiology, as their levels are altered in individuals with migraine." (PMID 35884650, 2022). "Most recently, however, we showed that serum levels of proinflammatory biomarkers including CRP, TNF-α, interleukin-6, NO, and malondialdehyde positively correlated with number of migraine headache days per month." (PMID 34991456, 2022). "It was reported that several major cytokines, such as TNF-α, IL-1β, and IL-6, were elevated in patients during migraine attacks." (PMID 35928284, 2022). "On one hand, it was observed that female migraineurs have increased levels of pro-inflammatory cytokines (TNF-α, IL-1β, IL-6, IL-8) during both the migraine attack and the migraine-free period." (PMID 35456034, 2022). "Although the etiology of migraine is not fully understood, there is some evidence of increased levels of IL-1β and TNF-α in migraine and chronic tension-type headache." (PMID 35323721, 2022). "In clinical studies, it has been found that the levels in serum of IL-6 and TNF-α in migraineurs are higher than those in normal people, suggesting that neuroinflammation plays a certain role in the pathological mechanism of migraine." (PMID 35033010, 2022). "Clinical evidence for enhanced TNF plasma levels during migraine attacks in patients support an important role of the cytokine in the pathogenesis of migraines." (PMID 36613527, 2022). "The plasma and CSF levels of these mediators (e.g., CGRP, TNFα, and IL-1β) are enhanced during migraine attacks." (PMID 35052756, 2021). "TNF levels increase after migraine pain onset and decrease progressively over time after the onset of the attack." (PMID 34112082, 2021). "TNF-α and IL-6 levels were significantly higher in migraine patients compared to healthy controls during and between attacks." (PMID 34112082, 2021). "During migraine attacks (ictal period), interleukin-1β (IL-1β), IL-6, IL-8, and tumor necrosis factor-α (TNF-α) are increased." (PMID 34445635, 2021). "In patients with migraine, peripheral levels of pro-inflammatory cytokines, such as interleukin-1β (IL-1β) and tumor necrosis factor-α, are known to be increased." (PMID 34445635, 2021). "Clinical studies focusing on gut microbial changes in migraine patients have also shown that dysbiosis can worsen migraine pain in a TNFα-dependent process." (PMID 33804088, 2021). "The results showed that emodin can alleviate the pain response of migraine rats and significantly reduce the levels of NO, CGRP, SP, TNF-α and cGMP in migraine rats." (PMID 34744735, 2021).
migraine (continued). "Although, the exact pathophysiology of migraine is not fully understood, the level of pro-inflammatory cytokines like tumor necrosis factor alpha (TNF α) and interleukin 1 Beta (IL 1β) have been increase in serum of patients during migraine attack." (PMID 34788304, 2021). "A study based on migraine patients from China demonstrated that they had higher levels of IL-6, IL-1β, and TNF compared to healthy controls." (PMID 33020432, 2020). "Leptin levels are also increased in correlation with pro-inflammatory cytokines IL-6 and TNF-a, which have also been found to be elevated in people with migraine." (PMID 32762643, 2020). "Proinflammatory cytokines such as IL-1β, IL-6, and TNF-α proved to have high concentrations in serum in patients with migraine, indicating that inflammation plays a significant role in migraine pathogenesis." (PMID 32516927, 2020). "It is known that some adipokines (such as leptin and adiponectin), interleukin 6 (IL-6) and tumor necrosis factor alpha (TNF-α), can act as mediators of inflammatory processes linked to persistence and progression of migraine." (PMID 32349653, 2020). "The migraine prevalence was also higher in patients treated with TNF-alpha inhibitors and in patients with RA accompanied by high inflammation." (PMID 32560321, 2020). "The mean TNF-α levels were significantly higher in patients who had migraine (1.19 vs. 0.92 pg/mL; p < 0.001), and IL-6 levels were almost significantly different (9.23 vs. 5.47 pg/mL; p = 0.05) compared to these parameters in the controls." (PMID 32019484, 2020). "Franceschini and coworkers reported that mRNA expression of TNF-α increased following migraine induction in animal models." (PMID 31870279, 2019). "Significant positive correlations between dysbiosis and CIMT, glycosylated hemoglobin, migraine severity and duration, tumor necrosis factor-alpha, and body mass index were found." (PMID 31888137, 2019). "Increased levels of serum TNF-α and interleukin (IL)-6 were also demonstrated during migraine attacks." (PMID 30442087, 2018). "Concentration of IL-6 is increased during the first 2 hours of migraine; moreover, IL-10 and tumour necrosis factor alpha (TNF-α) are also elevated during attacks." (PMID 27191890, 2016). "A number of recent observations concerning the association between TNF –308G>A and NOS3 +894G>T and migraine support a significant genetic component to predisposition toward this frequently undiagnosed disabling disorder, but the results are controversial." (PMID 26098763, 2015). "SNPs rs3093664 (TNF) and rs9371601 (SYNE1) were both significantly associated with migraine in the combined PMM-MRM sample and the MRM sample." (PMID 25315199, 2014). "This study was aimed at investigating genetic variants that are potentially related to MM, specifically undertaking genotyping and mRNA expression analysis of the ESR1, PGR, SYNE1 and TNF genes in MM cases and non-migraine controls." (PMID 25315199, 2014). "SNPs rs3093664 and rs9371601 in TNF and SYNE1 genes respectively, were significantly associated with migraine in the MM population (p = 0.008; p = 0.009 respectively)." (PMID 25315199, 2014). "Enhanced levels of pro-inflammatory cytokines like tumor necrosis factor alpha and interleukin 1β in serum of migraine patients have been found during migraine attacks." (PMID 25484876, 2014). "Inflammatory cytokines such as TNFα contribute to peripheral sensitization of nociceptor neurons, and in particular, in migraine patients, raised concentrations of TNFα have been reported in the jugular blood of patients 2 h after the onset of an attack." (PMID 23326332, 2013). "For instance, some studies demonstrated an increase of proinflammatory cytokines such as IL-6, IL-2, CGRP, and TNF in migraine." (PMID 23984350, 2013).
migraine (continued). "Since TNFSF7 is homologous to the ligands of the TNF receptor family i.e. TNF-alpha and TNF-beta, (and is localized to a migraine susceptibility area at C19p13) we decided to investigate this gene for association with migraine." (PMID 19018300, 2008). "Interestingly, we observed that TNFα was increased in migraine patients (0.34 ± 0.23 vs. 0.20 ± 0.05; p = 0.005), and when the chronicity of events classified these, all three cytokines were increased in CM patients." (PMID 41010614, 2025). "Elevated levels of miR-197, miR-101, and miR-143, along with proinflammatory cytokines (TNF-α, IL-6, and IL-17A), align with the hypothesis of migraine as an inflammatory process." (PMID 41010614, 2025). "Cytokine involvement in migraine has been extensively studied, particularly TNF-α and IL-1β." (PMID 40426647, 2025). "Small trials of etanercept (a TNF blocker) in migraine have been inconclusive so far, but interest remains in exploring immune-targeted therapies if suitable biomarkers can identify which patients might benefit." (PMID 41377228, 2025). "Does it mediate the chronicity of migraine by modulating inflammatory factors such as TNF and IL-6?" (PMID 39958329, 2025). "The same cytokines suffused during a migraine flare—IL-6, TNF-α, ROS—subvert antitumour surveillance; melatonin extinguishes these mediators, synchronises clock-gene–driven metabolism and stitches a biochemical thread between headache relief and cancer immunity." (PMID 40791587, 2025). "It is well-recognized that pro-inflammatory cytokines like Interleukin-(IL)-1β and tumor necrosis factor (TNF)-α may increase in migraine patients during or between attacks." (PMID 40149800, 2025). "In the current model for migraine induction, a significant elevation in the serum levels of substance P, NO, and TNF-α as well as brain levels of CGRP and c-fos was observed reflecting the success of the experimental model and induced hyperalgesia and matching earlier records." (PMID 39500819, 2025). "Indeed, TNFα can sensitize nociceptors and induce pain, while IL-6 is elevated in some migraine patients, especially during migraine attacks." (PMID 41010614, 2025). "For example, IL-17 was higher in CM vs. EM (9.46 ± 1.06 vs. 7.61 ± 2.12, p = 0.030), IL-6 in CM vs. non-migraine subjects (4.95 ± 2.84 vs. 1.52 ± 0.98, p = 0.016), and TNFα was higher in CM vs. non-migraine and EM subjects (0.46 ± 0.24 vs. 0.20 ± 0.05, p = 0.011 and vs. 0.20 ± 0.13, p = 0.016)." (PMID 41010614, 2025). "Notably, combination nutraceutical therapies (e.g., omega-3 plus nano-curcumin) led to significant declines in IL-1β, IL-6, and TNF-α, along with fewer migraine attacks." (PMID 41377228, 2025). "TNF-α (NCBI Entrez Gene: 7124) encodes for a pleiotropic cytokine that promotes a wide range of proinflammatory reactions and is responsible for various conditions including migraine (MalaCards—human disease database; OMIM—Online Mendelian Inheritance in Man)." (PMID 38213956, 2024). "Therefore, it is possible that aCL and β2GPI contribute to migraine with aura via TNF‐α‐mediated pathways." (PMID 38346716, 2024). "After adjusting for Diastolic blood pressure (OR [95% CI]: 1.4120 [0.8487–2.3493], p = 0.1840) and Tumor necrosis factor alpha (OR [95% CI]: 1.2411 [0.8352–1.8443], p = 0.2852), no discernible association was detected between migraine and the risk of AD." (PMID 38903170, 2024). "GERD may lead to dysbiosis of the gut microbiota, thereby affecting the levels of tumor necrosis factor-alpha and serotonin in the trigeminal nociceptive system, involved in the normal mechanical nociception and pathogenesis of migraine." (PMID 38990854, 2024). "Patients with migraines also have higher blood levels of TNF-α." (PMID 39416954, 2024). "Furthermore, according to available evidence, inflammatory factors such as interleukin (IL)‐1β, IL‐6, and tumor necrosis factor (TNF)‐α levels have also been shown to rise in patients with migraine, especially during migraine attack phases." (PMID 39055195, 2024).
migraine (continued). "However, the purpose of attempting to write this review is to better understand migraine as a neuroinflammatory disorder referring to TNF-α as an example." (PMID 38213956, 2024). "Increased blood levels of IL1β and TNF have been reported in migraine patients." (PMID 39009958, 2024). "Furthermore, elevated leptin level is thought to induce the secretion of pro-inflammatory factors (IL-6 and TNF- α) and NO that play a role in migraine through the NF-κβ signaling pathway." (PMID 38243194, 2024). "It has been suggested that proinflammatory mediators such as COX-2, TNF-α, and MMP9 could be viable pharmaceutical targets in the development of migraines caused by NO." (PMID 38836002, 2024). "Similarly, Sarchielli and his team found a temporary increase in TNF-α levels in the blood from the internal jugular in migraine patients who did not have an aura in the two hours following the start of their migraine." (PMID 38213956, 2024). "Compared to the control group, the migraine patients had increased levels of TNF-α in their blood." (PMID 39416954, 2024). "TNF-α is secreted by the microglial cell upon activation by the release of histamine and serotonin, and changes in the level of TNF-α across subjects can be a key risk factor for migraine susceptibility and severity." (PMID 38213956, 2024). "It is not only that the amount of the same has risen, which can be linked to the illness; there's also evidence from other chronic conditions, such as up-regulation of TNF levels in the trigeminal nociceptive pathway, that gut microbiota dysbiosis contributes to the chronicity of migraine-like pain." (PMID 38213956, 2024). "It has been also seen that TNF-a levels fluctuate more among children than in adults, and this difference might be due to a long medical history of migraine in adult patients and frequent intake of analgesic drugs or prophylactic treatment." (PMID 38213956, 2024). "TNF-α (NCBI Entrez Gene: 7124) encodes for a cytokine that promotes a diverse range of proinflammatory reactions and is responsible for various conditions including migraine (MalaCards—human disease database and OMIM—Online Mendelian Inheritance in Man)." (PMID 37085790, 2023). "The other study presented that serum IL-6, CRP, and TNF-α were significantly higher in subjects who developed chronic migraines compared to episodic migraines and controls, and a positive correlation between headache frequency and serum IL-6 and TNF-α was confirmed." (PMID 37176049, 2023). "In addition, pro-inflammatory cytokines such as interleukin (IL)-1β, IL-6, IL-8, and tumor necrosis factor-α (TNF-α) are increased during migraine attacks." (PMID 37755364, 2023). "In addition, increased secretion of serum cytokines (ILs, TNF-α)—an important regulator of inflammatory responsiveness—has been observed during migraine attacks." (PMID 37755364, 2023). "In the sound stress migraine model, women expressed higher levels of TNF-α, IL-6, and CGRP than men, suggesting that differences in inflammatory response might be involved in the sex differences in migraine." (PMID 37176049, 2023). "Therefore, the involvement of up-regulation TNF-α level contributes to the chronicity of migraine-like pain." (PMID 37460956, 2023). "It found that IL-1β, IL-6, and TNF-α were all higher in patients with migraine than controls." (PMID 37016284, 2023). "However, in a translational NTG migraine model, antibiotic administration induced prolonged pain was blocked by tumor necrosis factor alpha (TNF-α) targeted interventions." (PMID 37940864, 2023). "Moreover, intermediate-dose XZR had a similar beneficial effect, as it reversed the high levels of TNF-α (15.91 ± 6.93 pg/mg protein), IL-1β (38.20 ± 0.76 pg/ml), and IL-6 (17.76 ± 3.02 pg/ml) in rats with migraine (p < 0.05)." (PMID 35928284, 2022).